BDNF (brain derived neurotrophic factor)
Diseases named in the same sentence as BDNF in open-access papers (continued):
Sharing a sentence is not in itself a finding about the gene and the disease.
Cerebral ischemia (continued). "Another core acupoint, EX-HN1 (Sishencong), has been used for treating motor function after cerebral ischemia and was found to enhance the survival and specialized development of NG2-expressing cells through the stimulation of signaling pathways induced by the brain-derived neurotrophic factor." (PMID 39273805, 2024). "Interestingly PEA was shown to increase hippocampal neurogenesis and neuroplasticity in an established murine model of autism, and prevented the decrease in brain-derived neurotrophic factor (BDNF) and glial cell line-derived neurotrophic factor (GDNF) in a murine model of cerebral ischemia." (PMID 34069940, 2021). "However, whether ta-VNS could influence the expression of BDNF, VEGF, and p-eNOS through PPAR-γ in cerebral ischemia was unknown." (PMID 32775443, 2020). "Pre-clinical studies in rats showed that exercise could lead to increase in the production of BDNF and NGF in a cerebral ischemia model, and consequently potentiate the resistance of the animal against brain injury induction by cerebral ischemia (Ang, Wong, Moochhala, & Ng, 2003)." (PMID 28446953, 2017). "Furthermore, IGF-1 and BDNF might not be essential for activation of this pathway after severe cerebral ischemia." (PMID 27866373, 2017). "Additionally, low brain-derived neurotrophic factor (BDNF) protein levels in the hippocampus may contribute to deteriorative apoptosis of a subpopulation of hippocampal neurons, decreasing neuronal survival as well as impairing spatial learning and memory after cerebral ischemia." (PMID 28769792, 2017). "A very similar expression-changing pattern was observed for the NT-3 transcript, a member of the neurotrophin family like BDNF; however, the expression of NGF, another member of the neurotrophin family was not statistically affected by the cerebral ischemia or stem cell transplantation." (PMID 35879657, 2022). "In addition, as the protein levels of insulin-like growth factor-1 (IGF-1) and brain-derived neurotrophic factor (BDNF) were decreased, they might not have been essential for activation of the PI3-K/Akt/GSK-3β pathway after severe cerebral ischemia." (PMID 27866373, 2017).
ischemic stroke (192 papers, 2010 to 2026). A stroke disorder caused by obstruction of blood flow to the brain, due to thrombotic (local blood clot formation) or embolic (due to a blood clot or other material traveling from another site) event. "In ischemic stroke, lower blood concentrations of brain-derived neurotrophic factor (BDNF) have been linked to worse outcomes." (PMID 41893053, 2026). "A lower serum BDNF level predicted a greater cardiovascular risk, while several genotypic variants of BDNF were distinctly associated with ischemic stroke." (PMID 36782254, 2023). "In humans, serum BDNF levels were lower in the acute phases of ischemic stroke, suggesting that lower levels of BDNF were associated with a higher likelihood of cerebrovascular accidents." (PMID 37176155, 2023). "Some studies have also found that reduced BDNF levels are associated with severe functional impairment during the acute phase of ischemic stroke." (PMID 35177977, 2022). "Recent studies have suggested that VNS-mediated angiogenesis after an ischemic stroke is associated with the expression of angiogenic factors, such as brain-derived neurotrophic factor (BDNF), VEGF, and growth differentiation factor-11 (GDF11)." (PMID 36389255, 2022). "For example, brain-derived neurotrophic factor (BDNF) released from BMECs during ischemic stroke has been shown to protect against neuronal loss." (PMID 34067629, 2021). "Further, they determined that the risk of PSD development was much higher in ischemic stroke patients who were divorced or separated and who had lower levels of serum BDNF (p = .002)." (PMID 34141514, 2021). "In most of the paradigms in which exercise was studied as a prophylactic or as a therapy for ischemic stroke, the neuroprotective roles of exercise were associated with restoration of BDNF levels." (PMID 34108925, 2021). "In particular, we observed, in non-diabetic patients with TIA, that the decay of miRNA-195-5p 72 h after the ischemic stroke period was associated with a marked increase in BDNF serum levels." (PMID 33076256, 2020). "In patients with ischemic stroke and subarachnoid hemorrhage, the BDNF genotype has been associated with motor function." (PMID 33029116, 2020). "A recent genetic study reported that BDNF polymorphisms were associated with ischemic stroke in Chinese individuals with large-artery atherosclerosis." (PMID 32679912, 2020). "Especially, low circulating concentration of BDNF is associated with poor long-term functional outcome of ischemic stroke while intranasal BDNF protected against cerebral I/R injury." (PMID 29765412, 2018). "This is the first evaluation of the association between BDNF genotypes and long-term outcomes after ischemic stroke in a population of Western decent." (PMID 25470006, 2014). "The underlying mechanism for EA’s efficacy in ischemic stroke management may be attributed to the elevation of BDNF protein concentrations in both neural tissues and systemic circulation." (PMID 41517678, 2026). "Additionally, a multicenter study on patients with hypertension and ischemic stroke suggested that high serum BDNF levels were associated with a decreased incidence of PSCI at 3 months." (PMID 40821836, 2025). "Moreover, a novel therapeutic approach in neurodegenerative diseases and ischemic stroke targeting miRNAs associated with BDNF will be discussed." (PMID 32944919, 2021). "Moreover, in rats in which an ischemic stroke was induced, the brain BDNF increased, and the BDNF up-regulation was associated with motor function improvement." (PMID 33182716, 2020). "The brain-derived neurotrophic factor (BDNF) has been implicated in ischemic stroke pathogenesis." (PMID 33192177, 2020). "As far as we are aware, only one study has shown that BDNF variants are associated with long-term outcome (up to 1 years post-ischemic stroke,), and no study has yet looked at functional outcome exceeding 1 year after ischemic stroke." (PMID 25470006, 2014).
ischemic stroke (continued). "However, this study suggests that variants in the BDNF gene may contribute to poor long-term functional outcome after ischemic stroke." (PMID 25470006, 2014). "Accumulating research demonstrates that acupuncture intervention up-regulates BDNF expression to improve neurogenesis and promote functional recovery in ischemic stroke animal models." (PMID 41517678, 2026). "This is because non-neuronal cells are also able to produce substantial amounts of BDNF in the brain after ischemic stroke, although unilateral ischemic stroke increases BDNF content in both hemispheres." (PMID 40490588, 2025). "BDNF is considered a clinical biomarker for predicting PSD onset, while neuroinflammation and synaptic damage are key pathological changes linked to ischemic stroke." (PMID 40092064, 2025). "R1 promotes oligodendrogenesis after ischemic stroke by increasing the expression of BDNF, thereby improving CIRI and long-term neurological recovery after ischemic stroke." (PMID 41322290, 2025). "Needle insertion at “Baihui” and “Qubin” increases levels of brain-derived neurotrophic factor (BDNF) and improves functional and motor recovery after ischemic stroke." (PMID 39935855, 2025). "Genetic variations in BDNF function appear to be more closely related to early neurological deficits in patients with haemorrhagic stroke than in those with ischaemic stroke." (PMID 38707431, 2024). "Naïve HFSCs express different paracrine factors mainly the individual ones VEGF and BDNF being among them, whose neurotrophic privilege extensively demonstrated in the devastative conditions of ischemic stroke animal models." (PMID 38915453, 2024). "Excitingly, some studies are beginning to increase BDNF expression to promote recovery from ischemic stroke." (PMID 38817358, 2024). "Intrathecal VEGF-C pretreatment promotes lymphatic drainage of brain-derived fluids and improves neurological outcomes after ischemic stroke via reduced microglia-mediated neuroinflammation and increased BDNF signaling." (PMID 38442272, 2024). "The average serum BDNF level in individuals with haemorrhagic stroke is lower than that in individuals with ischaemic stroke." (PMID 38707431, 2024). "Ischemic stroke mice with VEGF-C prophylaxis showed decreased microglial/macrophage proinflammatory gene expression and increased BDNF signaling, associated with better outcomes with respect to lesion size and neurological tests at 3 d- and 7 d-pso." (PMID 38442272, 2024). "The effect of VEGF-C to promote BDNF signaling noted in the healthy adult mouse brain was amplified after ischemic stroke." (PMID 38442272, 2024). "The researchers also found that higher serum BDNF levels were correlated with a decrease in poor prognosis following ischemic stroke." (PMID 38397057, 2024). "Post-injury proliferation of OPCs has been previously studied [36,], and following ischemic stroke in mice BDNF administration resulted in increased OPC proliferation." (PMID 39428261, 2024). "Administration of galectin-1 to rats subjected to photochemical ischemic stroke enhanced the expression and secretion of astrocytic BDNF, reduced neuronal apoptosis in the ischemic boundary zone, and improved functional recovery." (PMID 37464832, 2023). "We found a significant decrease in the level of BDNF in the blood serum of patients with ischemic stroke both on the first and on the 14th day." (PMID 36969561, 2023). "In the present study, we found that the down‐regulation of Cav‐1 following the treatment of miR‐199a‐5p agomir was accompanied by the increased expression of VEGF and BDNF after ischemic stroke in rats." (PMID 37349971, 2023). "Chronic elevation of IL1β suppresses BDNF and is a potential therapeutic target in the treatment and recovery from ischaemic stroke." (PMID 35639336, 2023). "Statistically lower indicators of the BDNF level were established on the 1st day of ischemic stroke in group 1 compared to group 2 (р=0.029)." (PMID 36969561, 2023).
ischemic stroke (continued). "Decreased BDNF concentration in ischemic stroke is well known and confirmed by the latest meta-analysis." (PMID 36969561, 2023). "In this regard, previous studies have shown elevated levels of BDNF in the serum and cerebrovascular fluid of patients suffering from ischemic stroke, traumatic brain injury and encephalitis." (PMID 36766573, 2023). "The inverse Wald method was used to select 2-factor characteristics with a statistically significant effect: BDNF concentration for 1 day (X1) and atherothrombotic subtype of ischemic stroke (X2)." (PMID 36969561, 2023). "BDNF not only has an important role in promoting neuronal survival but also promotes neurogenesis after ischemic stroke." (PMID 36741282, 2023). "Brain-derived neurotrophic factor (BDNF) plays a significant role in the pathogenesis and rehabilitation of ischemic stroke and also affects the patients' recovery prognosis." (PMID 36969561, 2023). "RJ supplementation for 12 weeks in patients with ischemic stroke seems to be beneficial in terms of cognitive function, serum levels of BDNF, stress, and appetite." (PMID 38260068, 2023). "We found that RJ administration for 12 weeks in individuals with ischemic stroke was beneficial in improving cognitive function, serum levels of BDNF, stress, and appetite." (PMID 38260068, 2023). "In cases involving ischemic stroke, high levels of BDNF were induced during the acute phase while the subsequent decline appears to be strongly associated with clinical outcomes." (PMID 35887140, 2022). "In clinical practice, dynamic changes of MMP-9 and BDNF were superior to baseline measurement in predicting the prognosis of ischemic stroke." (PMID 36092813, 2022). "In mice, enhancement of AMPA receptor signaling by AMPA receptor agonists (CX 1837 and CX 1739) induced brain-derived neurotrophic factor secretion in periinfarct cortex and promoted motor function recovery after ischemic stroke." (PMID 36064798, 2022). "Previous studies explored the critical role that irisin played in ischemic stroke in mice models, indicating that irisin can upregulate the levels of brain-derived neurotrophic factor (BDNF) and protects nerve cells from injury during ischemic stroke." (PMID 35392928, 2022). "From a physiologic perspective, acupuncture treatment can facilitate recovery from ischemic stroke through neurogenesis by enhancing the brain-derived neurotrophic factor and vascular endothelial growth factor signaling pathways." (PMID 35627893, 2022). "BDNF, a key neurotrophic factor produced in the brain, has been proved to protect neurons and promote neurogenesis and synaptic plasticity during ischemic stroke." (PMID 35770087, 2022). "In ischemic stroke, BDNF plays a neuroprotective role in the regulation of signal pathways, the release of cytokines and the inhibition of apoptosis." (PMID 35462697, 2022). "This shows that BDNF levels in the acute phase of ischemic stroke possess a prognostic value for the patient’s functional status." (PMID 35055089, 2022). "Studies asserted that quercetin and berberine alleviated neuronal apoptosis of ischemic stroke in the rat by activating the BDNF-TrkB-PI3K/Akt signaling pathway to increase the expression of BDNF." (PMID 35388303, 2022). "Lasek Bal and colleagues studied the role of BDNF in the acute ischemic stroke phase in correlation with functional outcome measured with modified Ranking Scale (mRS) at 90 days." (PMID 33809965, 2021). "TrkB is located directly downstream of BDNF, and previous studies have shown that activated TrkB plays a neuroprotective function after ischemic stroke and traumatic brain injury." (PMID 34425835, 2021). "In this review, we present a comprehensive overview of the current knowledge of the association between BDNF and miRNAs as well as diagnostic/prognostic/therapeutic value of miRNAs in a range of CNS disorders—including AD, PD, HD, ALS, MS, and ischemic stroke." (PMID 32944919, 2021).
ischemic stroke (continued). "Previous studies suggested that EPCs promote angiogenesis and enhance myelin thickness in the ischemic stroke mice by secreting BDNF and bFGF." (PMID 33579354, 2021). "BDNF, the most abundant neurotrophin in the mammalian CNS, exerts neuroprotective effects in ischemic stroke." (PMID 34234667, 2021). "Understanding which factors mediate the protective effects of exercise in ischemic stroke and deciphering the involvement of BDNF signaling will allow us to fully harness exercise's therapeutic potential." (PMID 34108925, 2021). "MiR-210 upregulated mature-BDNF/pro-BDNF ratio shows that miR-210 can be a promising therapeutic approach for ischemic stroke." (PMID 32944919, 2021). "In this minireview, we will focus on how newly identified blood-borne exercise factors that induce hippocampal BDNF signaling to promote learning and memory formation are protective after ischemic stroke." (PMID 34108925, 2021). "In these studies, we found that MIF was neuroprotective in ischemic stroke models via the inhibition of neuronal cell apoptosis and induction of brain-derived neurotrophic factor (BDNF) expression." (PMID 33672416, 2021). "In the rat model of ischemic stroke, antisense BDNF oligonucleotide administration negated rehabilitation’s therapeutic effect on the recovery of skilled reaching." (PMID 32932791, 2020). "This study aimed to elucidate the possible role of BDNF during early recovery from ischemic stroke assisted by motor training." (PMID 32916851, 2020). "Ischemic stroke results in a reduction of peripheral BDNF levels, which is partly compensated by rehabilitation treatment." (PMID 32916851, 2020). "Wei and colleagues found that GB can up-regulate the expression of BDNF in ischemic stroke by evaluating the therapeutic effects of GB in transient middle cerebral artery occlusion mice and OGD/R-treated N2a cells." (PMID 32848639, 2020). "This study elucidated that BDNF is a crucial regulator of the beneficial effects conferred by irisin in ischemic stroke." (PMID 33414714, 2020). "The role of BDNF in the pathophysiology of ischemic stroke has been evaluated in animal and clinical studies, where the results were not conclusive." (PMID 31768951, 2020). "Overexpression of BDNF increases the survival rates of the transplanted NSCs and promotes neurological functional recovery in experimental ischemic stroke animal models." (PMID 33537297, 2020). "Fifty-eight patients diagnosed with ischemic stroke were classified according to the BDNF genotype into a Val (valine homozygotes) or Met (methionine heterozygotes and homozygotes) group." (PMID 33029116, 2020). "Recently, the transplantation of Noggin-modified bone marrow stromal cells (BMSCs) and/or brain-derived neurotrophic factor (BDNF) has also been reported as a potential therapeutic method for ischemic stroke in clinics." (PMID 30931325, 2019). "Brain-derived neurotrophic factor protein expression in reactive astrocytes has been shown to increase in ischemic stroke and after SCI." (PMID 31105589, 2019). "In permanent ischemic stroke, however, BDNF protein was found to be upregulated in the acute phase within the infarct core as well as in the surrounding peri-infarct areas." (PMID 31105589, 2019). "In conclusion, this study demonstrated that PCGE was effective in reducing neurotoxicity in ischemic stroke associated with decreasing H2O2-induced LDH release, upregulating HO-1, NQO-1, and BDNF expressions through activation of Nrf2 in brain cells." (PMID 29765502, 2018). "In conclusion, this study demonstrated for the first time that pretreatment with LIPUS by 15 min daily for 5 days effectively ameliorated the brain damage via BDNF induction in an ischemic stroke mouse model." (PMID 29615782, 2018). "For example, increased CREB activity and BDNF expression promote post-ischemic stroke neurogenesis and neuroregeneration in rats." (PMID 30208931, 2018).